LEP (leptin)
Diseases named in the same sentence as LEP in open-access papers (continued):
Sharing a sentence is not in itself a finding about the gene and the disease.
Obesity (continued). "However, the inability of POMC-ObRb deficient models to recapitulate Ob/Ob or Db/Db levels of diet-induced obesity (DIO) indicates a role for leptin signalling in energy homeostasis outside of the hypothalamic ARC-PVN circuit." (PMID 34613819, 2021). "Nevertheless, as proposed in animal studies, diet, sex, and other factors, such as age may influence development of obesity in LEP and LEPR heterozygotes." (PMID 34448070, 2021). "Our review found that the existing studies of obesity and osteoporosis mostly focus on obesity and the phenotypic regulation of osteoblasts and osteoclasts, and most of these changes are explained by adipokines, including leptin and adiponectin, signaling through paracrine and endocrine mechanisms." (PMID 34054735, 2021). "Even though these results underline the role of leptin during bacterial lung infection, they do not represent a clear link between obesity and lung infection." (PMID 33810619, 2021). "SHP2/ERK pathway, activated by phospho-Tyr985, controls also leptin’s anti-obesity function." (PMID 34356668, 2021). "In addition, the combinatorial effect of IL-33 with leptin, an obesity-related adipokine, promotes eosinophilic airway inflammation in obesity-related SA." (PMID 35387021, 2021). "Leptin and adiponectin could contribute to enhanced CVD risk through metabolic pathways related to obesity and insulin resistance, but could have independent effects as well." (PMID 34122163, 2021). "Resistance to diet-induced obesity, hypersensitive to leptin." (PMID 34502119, 2021). "Obesity is a risk factor for PCOS and leptin may have major pathologic roles in obese patients with PCOS." (PMID 34407095, 2021). "Leptin levels were increased before the OA changes, indicating that leptin may be a triggering factor for obesity-related OA." (PMID 34457118, 2021). "The proportion of microglia that express CCR2 also increases in obesity, which may indicate their activation, or chemoattraction toward areas with fenestrated capillaries and the gradient of increased leptin, free fatty acids, or insulin." (PMID 34154608, 2021). "Previous studies have reported that augmented leptin levels reduce nitric oxide availability and enhance superoxide generation attributing to impaired arterial vasodilation and reduced vessel distensibility in obesity." (PMID 34064112, 2021). "Obesity promotes a low-grade, chronic inflammation mediated by the secretion of hormones and cytokines, including leptin, which has been demonstrated to stimulate the production of pro-inflammatory cytokines in immune cells as well as inducing reactive oxygen species." (PMID 34827640, 2021). "Indeed, the production of many mediators of glucose metabolism by the adipose tissue (Non Esterified Fatty Acids, glycerol, leptin, and adiponectin; proinflammatory cytokines) are increased in obesity." (PMID 33467677, 2021). "It is well known that leptin is an important hormone related to obesity." (PMID 34128869, 2021). "Plasma leptin concentrations are higher in individuals with obesity compared with lean controls." (PMID 33804250, 2021). "Moreover, the interactions between age and obesity or between age and gender and the potential influence of leptin on REE are not completely understood." (PMID 33917063, 2021). "As evidenced by the compensatory increases in energy expenditure in the MTHF offspring, a role of leptin in mediating peripheral energy regulation is suggested, which may occur via the sympathetic nervous system during the development of obesity." (PMID 33925570, 2021). "Second, obesity-induced chronic inflammation and disruptions of insulin and leptin signaling can result in impaired viral clearance and a disproportionate or hyper-inflammatory response, which together with elevated ferritin levels can be a direct cause for ARDS and cytokine storm." (PMID 33920604, 2021).
Obesity (continued). "It was investigated whether phenolic compounds from grape could be beneficial for obesity by increasing the levels of leptin which can cross the blood-brain barrier." (PMID 34805304, 2021). "Adiponectin and leptin/adiponectin ratio also correlated with obesity (p < 0.05)." (PMID 34680168, 2021). "We and others demonstrated that leptin is a potent chemoattractant for macrophages, and the increased leptin in obesity may contribute to accumulation of macrophages in the adipose tissues." (PMID 34154608, 2021). "Overall, these results suggest that the inhibition of central and peripheral PTP1B using genetic circuits may overcome leptin and insulin resistance and provide an attractive strategy to combat obesity." (PMID 33782530, 2021). "Moreover, in obesity, leptin levels are chronically higher, leading to the desensitization of its receptors, and hence a hampered response of this hormone." (PMID 33672773, 2021). "It has recently been suggested that changes associated with Gabaergic neurons within the ARC may also contribute to obesity and possible leptin resistance." (PMID 35153807, 2021). "The main effects of insulin and leptin in states of obesity include sexually dimorphic alterations." (PMID 34084149, 2021). "This inflammatory response might contribute to a blunted physiological response to leptin in obesity even if overweight individuals have a higher circulating leptin level throughout the circadian rhythm." (PMID 34684349, 2021). "In obesity, as result of leptin resistance at central level, the sympathetic nervous system, which has a major anti-inflammatory role in the brain-immune cross-talk, results less activated, thus fostering obesity low-grade inflammatory background." (PMID 33804765, 2021). "The conclusion of this review will provide a basis for judging whether acupuncture therapy is effective in the treatment of leptin resistance in obesity." (PMID 34260523, 2021). "Bearing in mind that adiponectin and leptin secretion is markedly altered in obesity, it seems plausible to put forth the proposition that these hormones may present a role in the aggravation of COVID-19 in overweight patients." (PMID 34957187, 2021). "One study demonstrated that OSAS increases leptin levels independently of obesity." (PMID 34671315, 2021). "Leptin is a hormone produced primarily in the adipocytes of the white adipose tissue and is the key biomarker of the adipose tissue, which is closely related to obesity, diabetes, and metabolic syndrome." (PMID 33833859, 2021). "Vitamin A levels are directly associated with leptin, and higher vitamin A levels are present in women without obesity." (PMID 33670130, 2021). "Since IL-15 is produced by adipocytes, it should be hypothesized that leptin impairment, occurring during obesity, is directly involved in NK cell hyporesponsiveness in an mTOR-dependent manner." (PMID 35095876, 2021). "Additionally, obesity-related fat factors such as leptin are reported to be related to the occurrence and development of dyslipidemia." (PMID 34948819, 2021). "Mitochondrial fragmentation in the hypothalamus contributes to leptin resistance and obesity." (PMID 34231322, 2021). "In conclusion, maternal C-peptide and insulin sensitivity (ISHOMA), but not proxies of obesity such as BMI or leptin, associate with serum n-3 PUFA." (PMID 34638763, 2021). "In conclusion, obesity-associated immunometabolic factors including LDL-cholesterol, FABP4, and leptin were associated with a higher iNKT cell IFN-γ response across all disease groups, while HDL-cholesterol and insulin sensitivity (QUICKI) were associated with a higher IL-4 response." (PMID 34635725, 2021). "We and other authors have detected low-grade systemic inflammation, alterations indicative of endothelial dysfunction, and altered adipokine levels alongside the disorders that define MetS as well as an increase in leptin and decrease in adiponectin in children with obesity." (PMID 33665176, 2021).
Obesity (continued). "As the focus of this study was to construct a systematic obesity-relevant metabolic network, we first checked the child’s clinical and biological parameters (leptin, OGTT insulin AUC, adiponectin, FFA, TNF-α, FPG, and total cholesterol) that are thought to be related to a change in BMI." (PMID 34946095, 2021). "The hypothesis of this study is that individuals with obesity are more likely to have elevated leptin levels and inflammatory markers (including CRP, IL‐6, TNF‐α)." (PMID 33680494, 2021). "Examples of such gene mutations include those within SOX10 (KS in the context of Waardenburg-Shah syndrome), HESX1 (KS in the context of pituitary hormone deficiency and septo-optic dysplasia), NROB1 (ICH in the context of congenital adrenal dysplasia) and LEP (ICH in the context of obesity)." (PMID 34360982, 2021). "The finding that long-term use of imipramine may accelerate obesity through leptin signaling inhibition is valuable." (PMID 34564583, 2021). "In addition, the results of relevant study revealed that except for controlling of autoimmune inflammation, celastrol has the potential of pharmacological treatment of obesity as leptin sensitizer in silico drug screening methods." (PMID 33446184, 2021). "Hypothalamic resistance to the effects of leptin on the adipose tissue is essential for obesity." (PMID 34327017, 2021). "Leptin may act as a link between obesity, metabolism, an increased inflammatory milieu, cytokine production, and a dysregulated innate immune response." (PMID 35052684, 2021). "The biological significance of this hypermethylation is related to the dysregulation of leptin, leptin receptors, and the Agrp-Pomc system in the brain, and weight gain in offspring, which may lead to obesity later in life." (PMID 35052371, 2021). "While impairments attributed to leptin genetic mutations are treatable with recombinant methionyl human leptin administration, as result of leptin resistance replacement therapy in individuals with obesity does not provide therapeutic benefit." (PMID 33804765, 2021). "PTP-1B, a non-transmembrane PTP, down-regulate leptin/STAT3 signaling via indirectly inactivating JAK2, which may be a new target for the treatment of obesity induced by leptin resistance." (PMID 33849593, 2021). "Although several genetic analyses continue to provide evidence regarding the polymorphism that compromises the LEP/LEPR axis in an obesity setting, there are no comprehensive studies exploring the effects of SNPs on EE and thermoregulation." (PMID 34208585, 2021). "Because obesity is tightly linked to elevated leptin expression in mice, it was therefore not surprising that the authors found obesity to be associated with higher frequencies of PD-1+CD8+ TILs in melanoma tumors." (PMID 34421889, 2021). "Therefore, the ability of leptin to influence cardiovascular sympathetic nerve hyperactivity seems to be unaltered in obesity while being ineffective in regulating energy homeostasis." (PMID 34068919, 2021). "Conversely, a previous large-scale MR study on circulating adiponectin and five obesity-related cancer types does not support an association of tumor progression with concentrations of circulating adiponectin, leptin, sOB-R and PAI-1." (PMID 34458137, 2021). "In obesity, leptin resistance augments the production and secretion of leptin." (PMID 34593018, 2021). "This observational study was conducted to assess whether obesity, presented by a higher BMI and higher systemic leptin levels, is protective against DCI and results in better clinical outcomes." (PMID 33866464, 2021). "Moreover, MSG also altered metabolic activities related to hyperphagia with obesity which is also correlated with IR, increased levels of leptin (i.e., hyperleptinemia), and the altered ratio of bad cholesterol/good cholesterol (i.e., dyslipidemia)." (PMID 34026558, 2021). "In contrast, three others exhibited leptin levels comparable to other people with obesity." (PMID 33922961, 2021).
Obesity (continued). "Leptin, an adipocyte-produced hormone, plays an important role in obesity and its sequelae." (PMID 34276408, 2021). "We analyzed and compared the results for adiponectin, leptin, and the adiponectin/leptin ratio, to understand the endocrine physiology of adipose tissue response in COVID-19, considering the effect of the factors: obesity, sex, and age." (PMID 34957187, 2021). "However, individuals with obesity exhibit an impaired response to leptin despite their hyperleptinemia, suggesting a state of leptin resistance." (PMID 33917063, 2021). "Because of the higher serum levels in overweight people and the joint symptoms reduction by reducing weight in patients with OA, leptin may be presumed to be a necessary factor for obesity-related OA." (PMID 34457118, 2021). "Therefore, leptin should be considered a pivotal player in the development of obesity-related hypertension." (PMID 33761942, 2021). "Leptin together with other cytokines, could be promising new biological markers and therapeutic targets in obesity-related diseases." (PMID 35002761, 2021). "Although the cardiovascular safety of DPP-4 inhibitors has been proven in T2DM, the net effect of these drugs on leptin concentrations in obesity-related disease remains unclear." (PMID 34446063, 2021). "In obesity, the adipose tissue becomes hypertrophic and hyperplastic, triggering increased production of pro-inflammatory adipokines, such as tumor necrosis factor α, interleukin 6, interleukin 1, and leptin." (PMID 34283044, 2021). "The same group of authors, in a more recent paper found that the gravitostat regulates fat mass in obese mice, while leptin regulates fat mass in lean mice, concluding that the gravitostat protects against obesity, whereas undernutrition induces low levels of leptin, with subsequent weight gain." (PMID 34948466, 2021). "The discovery of leptin has provided new insight into how to control obesity." (PMID 34084149, 2021). "To date, most data concerning the cellular and molecular mechanisms of obesity-associated leptin resistance have been obtained in experimental rodent models, including DIO, genetic models, obesity-prone models, early overfeeding and age-related obesity animals with hypothalamic lesions." (PMID 34208585, 2021). "Obesity is also associated with elevated serum leptin levels, with many obese individuals experiencing ‘leptin resistance’ in which leptin is no longer able to effectively regulate food intake." (PMID 34572888, 2021). "For example, in human with and without obesity, lower bacterial richness is associated with higher circulating leptin concentrations." (PMID 34284827, 2021). "However, recently IL1R1 has been identified as one of the key mediators in leptin sensitivity and IL1R1 deficiency leads to a higher degree of obesity and metabolic disturbance." (PMID 34372849, 2021). "Given the abundance of both in the obese state, the contribution of leptin to the obesity-associated immunopathology should not be underestimated and warrants further investigation." (PMID 34613819, 2021). "Leptin has been extensively identified as a potential molecule involved in obesity-related cancer." (PMID 33397392, 2021). "In conditions such as obesity, bacterial signals from the gut might compete with increased plasma levels of anorexigenic hormone signals like leptin while prebiotic treatment improved leptin sensitivity." (PMID 34444741, 2021). "Amongst them, leptin, ghrelin, insulin growth factor 1 (IGF-1), adiponectin and insulin have the most significant influence on the infant’s growth and body composition and, as a result, on the risk of obesity in adulthood." (PMID 34682128, 2021). "Another important issue is that the levels of leptin are usually higher in patients with obesity." (PMID 34690923, 2021). "It suggested that DPP-4i did not exert an effect on leptin resistance in T2DM patients with obesity-associated cardiovascular diseases." (PMID 34446063, 2021).
Obesity (continued). "Obesity-related leptin secretion may aggravate the carcinogenic effect of obesity on BC through the regulation of the cellular oxidative state." (PMID 34350120, 2021). "Previous works with mice and rats demonstrated that an increasein maternal blood leptin level increased the resistanceto diet-induced obesity in the offspring, and the programmingaction of maternal leptin might depend on the offspringsex." (PMID 34782887, 2021). "Summary of some clinical trials involving the use of leptin-based therapies to treat obesity." (PMID 34084149, 2021). "Recent studies have evidenced that high levels of leptin produced by obesity-altered ASCs derived from human lipoaspirate of SAT isolated from obese women promote TNBC cell migration and metastasis as well through induction of EMT process as well as growth and metastasis in ERα-positive BC." (PMID 33916703, 2021). "Research on how leptin relieves obesity has made great progress since its discovery in 1994." (PMID 34638947, 2021). "Similarly, mutations can cause a deficiency of leptin in humans, leading to increased appetite and resulting in severe obesity, thereby suggesting that leptin plays an important role in maintaining energy metabolism." (PMID 33868169, 2021). "Meanwhile, several reports have shown that α-linolenic acid could alleviate obesity and reduce the levels of inflammatory markers, such as serum insulin and leptin, and improve cholesterol homeostasis." (PMID 34950689, 2021). "The relationship between obesity and precocity may be mediated through leptin and its interaction with kisspeptin signaling, which is an important regulatory system in adolescence." (PMID 34456870, 2021). "Overall, leptin is emerging as the most important molecular mediator of the obesity-BC axis." (PMID 34350120, 2021). "Furthermore, compelling evidence shows that leptin signaling play an indispensable role in obesity-promoted tumorigenesis." (PMID 33535537, 2021). "Likewise, the orexigenic and anorexigenic hormones ghrelin and leptin, characteristically affected by obesity, were also found to be correlated with melatonin at night." (PMID 34684629, 2021). "Interestingly, SLR characterizes preservation of sympathetic nerve activity (SNA) in the kidney and normal blood pressure (BP) responses to leptin action in obesity, despite alterations in responses to leptin in appetite, thermogenesis, and body mass." (PMID 34084149, 2021). "In obesity, while leptin production increases, the level of adiponectin decreases." (PMID 34057306, 2021). "Among these, telmisartan (TEL) was shown to exert favourable metabolic benefits by preventing hypothalamic inflammation and by enhancing leptin transport through the BBB, thus restoring leptin sensitivity and counteracting the development of obesity under excess nutrient intake." (PMID 34208585, 2021). "Increased SOCS3 expression as a result of SARS-CoV-2 infection could therefore further impair leptin signaling and negatively influence the immune response in patients suffering from obesity." (PMID 33920604, 2021). "Finally, we have recently shown that obesity progression in DIO mice alters leptin signaling in the ovary with increased leptin signaling in the ovary of 4 wk DIO mice, being followed by the establishment of leptin resistance in the ovaries of 16 wk DIO mice." (PMID 33924072, 2021). "This study might be an ideal model for assessing the effects of leptin and obesity per se separately in an IL-33-induced asthma model." (PMID 34074279, 2021). "Central administration of oxytocin reduces body weight in animal models that are otherwise resistant to leptin (either because of their diet‐induced obesity or as a result of defective leptin signalling), with a concomitant improvement in glucose tolerance and insulin sensitivity." (PMID 34495565, 2021). "However, some evidence has suggested its beneficial role, called the “obesity paradox”, and the possible antitumoral role of leptin." (PMID 34202969, 2021).